SRP9P1 (signal recognition particle 9 pseudogene 1)
Synonyms: formerly SRP9L1
Gene: Processed pseudogene on chromosome 10 (91,807,179 to 91,807,439, reverse strand). Ensembl gene ENSG00000180581.
Diseases named in the same sentence as SRP9P1 in open-access papers:
SRP9P1 is named in the same sentence as 1 disease in open-access papers, as found by Europe PMC text mining. Sharing a sentence is not in itself a finding about the gene and the disease.
SRP9P1 shares sentences with these, for which no sentence is quoted: melanoma (1 paper).